PRL (prolactin)
Diseases named in the same sentence as PRL in open-access papers (continued):
Sharing a sentence is not in itself a finding about the gene and the disease.
prostate (3 papers, 2019 to 2024). "It is known that there is a relationship between the increase of prolactin levels and the increase of prostate diseases in men, and also that prolactin is responsible for the development of inflammation in the male gland." (PMID 34158080, 2021). "Additional observations supporting the role of PRL/STAT5 signaling in prostate tumorigenesis and cancer progression can be found in various review articles published within the last decade." (PMID 31269779, 2019). "Taken together these data indicate that the deletion of STAT5 delayed, but could not prevent the appearance of histopathological hallmarks of PRL-driven prostate tumorigenesis." (PMID 31269779, 2019). "In order to elucidate the actual contribution of STAT5 signaling in the various hallmarks of PRL-induced prostate tumorigenesis, we took advantage of previously developed floxed Stat5a/b mice to abolish STAT5 expression in the epithelial cells of Pb-PRL mice." (PMID 31269779, 2019).
prostate disease (3 papers, 2006 to 2022). "Similar to the Mt-PRL model, the BK5-IGF1 model may be adequate to model prostate disease, but the off-target effects of the transgene would be cause for concern when interpreting results." (PMID 22111002, 2011). "PRL levels increase with age and during prostate hyperplasia." (PMID 22111002, 2011).
rectal cancer (3 papers, 2011 to 2020). A primary or metastatic malignant neoplasm that affects the rectum. "Previous studies showed that TEM1 expression in tumor cells was positively related to PRL expression, whereas weak PRL-3 expression predicts favorable survival in rectal cancer patients with preoperative RT." (PMID 33123477, 2020). "Strong PRL expression could predict resistance to radiotherapy and unfavourable survival in rectal cancer patients with preoperative radiotherapy." (PMID 26013439, 2015). "Endosialin expression may be involved in the progression of rectal cancers, and was related to Cox-2, p73 and PRL expression." (PMID 21362178, 2011).
seborrhea (3 papers, 2020 to 2022). "Moreover, excess circulating growth hormone, thyroxine, or prolactin has been shown to cause increased sebum production (seborrhea)." (PMID 36552842, 2022).
Seizure (3 papers, 2019 to 2025). A seizure is an intermittent abnormality of nervous system physiology characterized by a transient occurrence of signs and/or symptoms due to abnormal excessive or synchronous neuronal activity in the brain. "PRL is elevated after epileptic seizures and syncope and quickly returns to baseline levels, which limits its value in the daily clinical practice." (PMID 31819916, 2019). "Several putative biomarkers (prolactin, neuron specific enolase, βS-100) have been identified to distinguish psychogenic non-epileptic seizures (PNES) from epileptic seizures, thereby improving initial diagnosis." (PMID 40495047, 2025).
trauma (3 papers, 2022 to 2025). "Compromised levels of hormones and proteins such as oxytocin and prolactin, which are associated with physical aspects of parenting (e.g., breastfeeding, birthing, parent–baby bonding), have been found in adult trauma survivors, affecting parenting on a biological level." (PMID 40238309, 2025). "The present study found that the IL-6 expression in PrL was significantly increased on weeks 5 after SNI, and the knockdown of IL-6R in pyramidal neuron of PrL relieved the depression-like behavior induced by nerve injury." (PMID 35690777, 2022).
triple-negative breast carcinoma (3 papers, 2019 to 2025). An invasive breast carcinoma which is negative for expression of estrogen receptor (ER), progesterone receptor (PR), and human epidermal growth factor receptor 2 (HER2). "Similarly, in triple-negative breast cancer cells (MDA-MB-231), the levels of human epidermal growth factor receptor 2 (Her2), prolactin (PRL), estrogen receptor (ER), and progesterone receptor (PR) were elevated following VDAC1 depletion." (PMID 39456237, 2024). "In triple-negative breast cancer of women (negative for ER, PR and HER2), the detection of certain components of the prolactin signaling pathway has likely prognostic significance." (PMID 31581718, 2019).
varicocele (3 papers, 2020 to 2023). A condition characterized by the dilated tortuous veins of the spermatic cord with a marked left-sided predominance. "All the variables from the preoperative assessment were included, with missing data in the training cohort ranging from 5.7% (10/175) to 57.7% (101/175) for varicocele and prolactin, respectively." (PMID 37342078, 2023). "In addition, serum prolactin concentration (mean 3.1%, SD 1.1%), patient age (mean 3.2%, SD 0.8%), and the presence of a history of varicoceles (whatever the grade; mean, 2.3%, SD 0.4%) also seemed to be important in discriminating between the 2 groups." (PMID 37342078, 2023).
venous thromboembolism (3 papers, 2013 to 2023). Occlusion of the lumen of a vein by a thrombus that has migrated from a distal site via the blood stream. "These same investigators have also found increased levels of prolactin in patients with venous thromboembolism, ischemic stroke and transient ischemic attack compared to the healthy subjects." (PMID 26886093, 2016). "Increased plasma levels of prolactin should probably be taken into account during the monitoring of antipsychotic treatment as well as in future research concerning venous thromboembolism in psychiatric settings." (PMID 23533901, 2013). "These same investigators have also found increased levels of prolactin in patients with venous thromboembolism (VTE) without any congenital and acquired thrombotic risk factors for VTE compared to the healthy subjects." (PMID 26886093, 2016).
Venous thrombosis (3 papers, 2016 to 2024). Formation of a blood clot (thrombus) inside a vein, causing the obstruction of blood flow. "This correlation underscores the importance of considering hormonal influences, particularly prolactin and leptin, in the context of thrombosis risk when using antipsychotic medications." (PMID 38255892, 2024). "have reported that venous thrombosis is associated with high prolactin levels." (PMID 26886093, 2016).
Yersinia infection (3 papers, 2022 to 2025). "It involves prolactin signaling pathway, estrogen signaling, proteoglycans in cancer, thyroid hormone signaling pathway, endocrine resistance, apoptosis, platelet activation, VEGF signaling pathway, Yersinia infection, etc." (PMID 36401485, 2022).
abortion (2 papers, 2021 to 2024). the ending of pregnancy by removing a fetus or embryo before it can survive outside the uterus. "Consistent with previous studies, we found that decidualization was impaired in abortion patients, as shown by abnormal morphology and downregulation of the decidual markers IGFBP1 and PRL." (PMID 38769534, 2024).
Addison’s disease (2 papers, 2013 to 2024). "TSH, prolactin, and a morning cortisol level will help to differentiate primary adrenal insufficiency from primary pituitary insufficiency." (PMID 24278787, 2013).
amyotrophic lateral sclerosis (2 papers, 2019 to 2025). Amyotrophic lateral sclerosis (ALS) is a neurodegenerative disease characterized by progressive muscular paralysis reflecting degeneration of motor neurons in the primary motor cortex, corticospinal tracts, brainstem and spinal cord. "Amyotrophic Lateral Sclerosis patients were separated according to PRL, into slow progressing (PRL < 0.5; n = 23) versus fast progressing (PRL > 0.5; n = 17)." (PMID 31037054, 2019).
Anterior hypopituitarism (2 papers, 2017 to 2021). A condition of reduced function of the anterior pituitary gland characterized by decreased secretion of one or more of the pituitary hormones growth hormone, thyroid-stimulating hormone, adrenocorticotropic hormone, prolactin, luteinizing hormone, and follicle-stimulating hormone. "In humans, POU1F1 mutations cause anterior hypopituitarism (deficiency of prolactin, thyrotropin and the growth hormone) and absence/delay of adrenarche and pubarche." (PMID 28125592, 2017). "The full pituitary profile screen showed profound anterior hypopituitarism with a prolactin level of 67,168 miu/L (normal range 86-324 miu/L)." (PMID 35070533, 2021).
arteriosclerosis (2 papers, 2020). A vascular disorder characterized by thickening and hardening of the walls of the arteries. "Furthermore, prolactin may accelerate arteriosclerosis in women in early menopause by increasing central as well as peripheral blood pressure and arterial stiffness." (PMID 33396861, 2020).
Ascites (2 papers, 2024 to 2025). Accumulation of fluid in the peritoneal cavity (between the layers of the peritoneum that lines the abdomen). "The Kruskal-Wallis test demonstrated a significant association between serum prolactin levels and the severity of ascites (p < 0.001) and hepatic encephalopathy (p < 0.001)." (PMID 39925608, 2025). "Twelve patients (8.0%) had ascites, with seven (58.3%) of them having normal prolactin levels and five (41.7%) showing increased levels (p=0.263)." (PMID 39650982, 2024). "Furthermore, serum prolactin levels were significantly elevated in patients with complications such as HE, ascites, and oesophageal varices." (PMID 39925608, 2025). "Elevated serum prolactin levels were observed in 77.4% of patients (n=60) with oesophageal varices, 88.2% (n=30) with upper gastrointestinal bleeding, 93.7% (n=39) with hepatic encephalopathy, 75.5% (n=53) with moderate to severe ascites, and 82.8% (n=3) with spontaneous bacterial peritonitis." (PMID 39925608, 2025). "Patients without ascites had a mean prolactin level of 20.58 ± 3.53 ng/mL, while those with mild to moderate ascites had 34.79 ± 7.13 ng/mL, and those with severe ascites had 38.10 ± 8.52 ng/mL." (PMID 39925608, 2025).
atopic dermatitis (2 papers, 2014 to 2025). "On the other hand, the thermal effect of thermal water also play major role in treating skin diseases by increasing production of cortisol, β-endorphins, prolactin, norephinephrine, adrenocorticotropic hormone and prolactin and also decrease basophils degranulation in patients of atopic dermatitis." (PMID 40423748, 2025). "In a study from Libya, it was demonstrated that serum prolactin levels were significantly higher in patients with mild to moderate psoriasis vulgaris compared to the serum levels of prolactin in patients suffering from atopic dermatitis and those of a control group." (PMID 24707406, 2014). "Prolactin does not seem to play a role in the pathogenesis of psoriasis vulgaris as its serum level is comparable with atopic dermatitis patients and that of healthy controls (all within the normal range)." (PMID 24707406, 2014). "In the atopic dermatitis group, the mean serum prolactin level was 330.54 mlU/L with a range of 190–471 mlU/L, and none had an elevated serum prolactin level." (PMID 24707406, 2014).
Brain atrophy (2 papers, 2023 to 2025). Partial or complete wasting (loss) of brain tissue that was once present. "In previous studies, patients with at least one PRL presented lower cortical gray matter volumes and higher brain atrophy rates." (PMID 40131429, 2025).
breast cyst (2 papers, 2016). A fluid-filled closed cavity or sac that is lined by an EPITHELIUM and found in the BREAST. "These factors include a previous history of trauma or inflammation leading to breast cyst formation in the neonatal period, previous or present stimulation by prolactin, the presence of secretory breast epithelium, and ductal obstruction." (PMID 27752383, 2016).
Carney complex (2 papers, 2019 to 2020). Carney complex (CNC) is characterized by spotty skin pigmentation, endocrine overactivity and myxomas. "To date, the regulatory Iα subunit has been of particular interest in the pituitary as mutations mapping to its locus at 17q22-24 are commonly found in patients with Carney Complex, a multiple neoplasia syndrome which is associated with abnormal GH and prolactin secretion." (PMID 32111982, 2020). "Pituitary adenomas occur in 10 to 20% of patients with Carney complex, most are GH secreting tumours but some of them co-secrete GH and PRL." (PMID 31847209, 2019).
cholestasis (2 papers, 2007 to 2023). Impairment of the bile flow caused by obstruction within the liver, or outside the liver in the bile duct system. "In the cholestasis of pregnancy, prolactin and its receptors are involved in water-salt metabolism and in turn, affect liver bile excretion." (PMID 37432229, 2023). "Thereupon, the effects of FS on HIF-1, prolactin, and relaxin, and the relationships between these effects and cholestasis need to be validated and explored in more depth in the future." (PMID 37432229, 2023). "However, in BDL, which is accompanied by an inflammatory response along with cholestasis, the blocking of prolactin with an antibody reduces hepatic damage and cholangiocyte proliferation along with suppression of some inflammatory responses." (PMID 17640386, 2007).
coagulation disorder (2 papers, 2021 to 2024). "But coagulation disorder should be kept an eye on, and the prolactin level can be interfered with if retained too high, especially for male patients, which can not only reduce inflammation to a certain extent but also relieve related long-term complications." (PMID 38503738, 2024).
colorectal adenocarcinoma (2 papers, 1992 to 2024). The most common type of colorectal carcinoma. "From our results, we suggest that PRL can be used as a better overall marker for detecting recurrence(s) in patients with colorectal adenocarcinoma." (PMID 1419646, 1992).
Combined Pituitary Hormone Deficiency (2 papers, 2016 to 2025). "Variants in the POU1F1 gene are associated with combined pituitary hormone deficiency 1 (CPHD1), which manifests as deficiencies in growth hormone (GH), thyroid-stimulating hormone (TSH), and prolactin (PRL)." (PMID 40141050, 2025). "Mutations in POU1F1 cause Combined Pituitary Hormone Deficiency (CPHD), which is typically characterized by lack of GH, TSH and PRL, while mutations in PROP1 cause progressive hormone deficiency that can include GH, TSH, PRL, gonadotropins and ACTH." (PMID 27685990, 2016).
coronary arterial disease (2 papers, 2014 to 2022). "Sex-specific associations have been reported also for other CV risk factors, including those between elevated plasma levels of sTNF-receptors and coronary heart disease, between uric acid and atrial fibrillation and between prolactin and cardiac remodeling." (PMID 25200659, 2014).
cystic fibrosis (2 papers, 2015 to 2023). Autosomal recessive disorder caused by pathogenic variants in the CFTR gene (cystic fibrosis transmembrane conductance regulator), which encodes a chloride and bicarbonate channel expressed in epithelial cells, and follow the diagnosis criteria. "Cystic fibrosis carrier testing, rubella immunity, thyroid studies, and prolactin were normal." (PMID 25737742, 2015).
Encephalopathy (2 papers, 2025). Encephalopathy is a term that means brain disease, damage, or malfunction. "Higher prolactin levels were associated with more severe grades of encephalopathy and increased mortality." (PMID 39925608, 2025). "Research has shown that median PRL levels rise in correlation with the severity of encephalopathy, indicating a direct relationship between PRL concentrations and the deterioration of liver function." (PMID 41476991, 2025). "Patients without HE had a mean prolactin level of 28.8 ± 6.35 ng/mL, while levels increased progressively with grades 1, 2, and 3 encephalopathy (34.53 ± 9.04 ng/mL, 43.71 ± 5.61 ng/mL, and 43.2 ± 5.45 ng/mL, respectively, p < 0.001)." (PMID 39925608, 2025).
gangliocytoma (2 papers, 2013 to 2025). A well differentiated, slow growing neuroepithelial neoplasm composed of neoplastic, mature ganglion cells. "In 1999, positive IH for PRL was described in a patient with gangliocytoma." (PMID 23317095, 2013).
gastroesophageal reflux disease (2 papers, 2020 to 2025). A chronic disorder characterized by reflux of the gastric and/or duodenal contents into the distal esophagus. "Prolactin is involved in immune response and is upregulated in inflammatory esophageal conditions such as gastroesophageal reflux disease." (PMID 39808500, 2025).
hair diseases (2 papers, 2013 to 2024). "Given the major endocrine functions of skin, a source and target of PRL, and that PRL is a potential player in skin and hair diseases a comprehensive analysis of the intracutaneous regulation of PRL and PRLR is required." (PMID 23626671, 2013). "Therefore, given that PRL modulated human HF biology, and bearing in mind its role as a stress hormone, it was conceivable that PRL played a role in stress-mediated hair diseases." (PMID 39000207, 2024). "Given the range of physiological, pathological, genetic and medication-related factors that can influence serum PRL concentrations, failure to control for these factors may partially explain discrepancies between studies examining the role of PRL in skin disease and hair disorders." (PMID 39000207, 2024).
hearing loss (2 papers, 2013 to 2019). "This provided an indication that PRL expression was potentially linked to abnormal bone metabolism or degeneration of other structures within the cochlea leading to an age-related hearing loss (ARHL) pathology." (PMID 23667691, 2013). "Therefore, in this study we have investigated for the presence of PRL and its association to hearing loss in a cohort of BALB/c mice." (PMID 23667691, 2013).
hemorrhage (2 papers, 2016 to 2017). Loss of blood from the vascular compartment to the exterior or into nonvascular body space as a result of rupture or severance of the blood vessels. "Of particular interest would be situations expected to require functional state transitions to produce large secretory responses such as osmotic/hemorrhage challenge, stress-induced ACTH release, suckling-induced prolactin/OT release, or pulse/surge of LH." (PMID 27065780, 2016).
Hypercalcemia (2 papers, 2021 to 2025). An abnormally increased calcium concentration in the blood. "Laboratory examinations revealed high serum concentrations of GH and PRL with mild hypercalcemia, hyperphosphatemia, hypercalciuria, inhibited PTH concentration, and increased bone turnover markers." (PMID 33933067, 2021). "Here we present a case of non-PTH-dependent hypercalcemia associated with a growth hormone- (GH) and prolactin- (PRL) co-secreting pituitary macroadenoma." (PMID 33933067, 2021).
Hypernatremia (2 papers, 2023 to 2025). An abnormally increased sodium concentration in the blood. "Laboratory findings showed hypernatremia (Na 155.7–157.5 mmol/L), hyperchloremia (Cl 113.6–119.1 mmol/L), low TSH (0.015–0.144 μIU/mL) with low-to-normal FT3/FT4, persistently low cortisol, low FSH/LH, and low PRL." (PMID 41189157, 2025).
hypertriglyceridemia (2 papers, 2023 to 2024). A laboratory test result indicating elevated triglyceride concentration in the blood. "Treatment-emergent hypertriglyceridemia (7.1%), increases in prolactin (58%), and corrected QT interval (≥30 ms, 12%) were also common in the OFC group." (PMID 36595095, 2023).
immunodeficiencies (2 papers, 2013 to 2023). "Differently, severe immunodeficiency is observed in another form of GH insensitivity due to a mutation in the signal transducer and activator of transcription 5B (STAT5B) gene, with reduced IGF-1 production, impaired response to infections and high production of prolactin (PRL)." (PMID 37426675, 2023).
influenza (2 papers, 2024 to 2025). An acute viral infection of the respiratory tract, occurring in isolated cases, in epidemics, or in pandemics; it is caused by serologically different strains of viruses (influenzaviruses) designated A, B, and C, has a 3-day incubation period, and usually lasts for 3 to 10 days. "Gene regulation analysis in the mammary gland demonstrated downregulation of milk production genes, including PRL, suggesting a potential viral interference mechanism disrupting lactation processes during influenza infection." (PMID 41476991, 2025).